TPGS2 (tubulin polyglutamylase complex subunit 2)
Description:
Subunit of the tubulin polyglutamylase complex (TPGC). The complex mediates cilia and flagella polyglutamylation which is essential for their biogenesis and motility.
Synonyms: PGs2; C18orf10; HMFN0601; L17; DKFZP586M1523; HsT3006
Tractability: PROTAC: ubiquitination databases record sites on it.
Gene: Protein-coding gene on chromosome 18 (36,777,647 to 36,829,216, reverse strand). Ensembl gene ENSG00000134779.
Subcellular location: Cytoplasm, cytoskeleton; Cytoplasm, cytoskeleton, microtubule organizing center, centrosome, centriolar satellite
Pathways (Reactome):
Metabolism of proteins: Carboxyterminal post-translational modifications of tubulin
Gene Ontology:
Molecular function: protein binding; protein-macromolecule adaptor activity
Biological process: microtubule cytoskeleton organization
Cellular component: microtubule; catalytic complex; centriolar satellite; cytoskeleton
Genetic constraint (gnomAD): Loss-of-function variants: 27 observed, 34.21 expected, observed/expected ratio (o/e) 0.79, 90% interval 0.58 to 1.09. The upper end of that interval is the gene's LOEUF score, 1.09, which puts it in group 4 of 6, group 1 being the genes least tolerant of losing a copy. Missense variants: 351 observed, 384.35 expected, observed/expected ratio (o/e) 0.91, 90% interval 0.84 to 1. Synonymous variants: 130 observed, 143.93 expected, observed/expected ratio (o/e) 0.9, 90% interval 0.78 to 1.04.
Homologues: Orthologues: dog TPGS2 (89% identical), pig TPGS2 (89% identical), guinea pig TPGS2 (86% identical), mouse Tpgs2 (85% identical), rat Tpgs2 (84% identical), rabbit TPGS2 (82% identical), chimpanzee TPGS2 (79% identical), macaque TPGS2 (78% identical), tropical clawed frog tpgs2 (59% identical), zebrafish tpgs2 (51% identical), Drosophila melanogaster CG6931 (26% identical).
Diseases named in the same sentence as TPGS2 in open-access papers:
TPGS2 is named in the same sentence as 8 diseases in open-access papers, as found by Europe PMC text mining. Sharing a sentence is not in itself a finding about the gene and the disease. The quoted sentences say what the papers report.
epilepsy (2 papers, 2023 to 2025). A brain disorder characterized by episodes of abnormally increased neuronal discharge resulting in transient episodes of sensory or motor neurological dysfunction, or psychic dysfunction. "MR analysis identified causal relationships, such as NBL1 in epilepsy, TPGS2 in ischemic stroke, and SERINC2 in VaD." (PMID 40624693, 2025). "Additionally, our MR analysis identified causal relationships between specific genes and disease outcomes, such as NBL1 in epilepsy, TPGS2 in ischemic stroke, and SERINC2 in VaD." (PMID 40624693, 2025). "In consideration of species conservation, we jointly analyzed the sequencing results of human peripheral blood samples and mouse tissue samples, and four genes (GADD45B, TMCC3, TPGS2, and KCNJ2) were identified as hub genes in IS and epilepsy." (PMID 37792772, 2023). "However, the involvement of TMCC3 and TPGS2 in IS and epilepsy has not been elucidated." (PMID 37792772, 2023).
ischemic stroke (1 paper, 2025). A stroke disorder caused by obstruction of blood flow to the brain, due to thrombotic (local blood clot formation) or embolic (due to a blood clot or other material traveling from another site) event. "The IVW model results indicated a significant causal relationship between TPGS2 and ischemic stroke (OR = 0.891, 95% CI = 0.826–0.962, p = 0.003), suggesting that an increase in the exposure factor is causally linked to a decrease in the outcome measure." (PMID 40624693, 2025). "In the MR analysis with ischemic stroke as the outcome, we identified 20 positive results, including myeloperoxidase (MPO), CALCRL, and TPGS2." (PMID 40624693, 2025).
schizophrenia (1 paper, 2024). A major psychotic disorder characterized by abnormalities in the perception or expression of reality. "ARL17B is implicated in schizophrenia, TPGS2 is found in the microtubule gene ontology term, and PRKAG2 is part of 4 pathways (AMPK signaling pathway, Lysine degradation, Cholinergic synapse, GnRH secretion) as well as the protein serine/threonine kinase activity gene ontology term." (PMID 38532526, 2024).
TPGS2 also shares sentences with these, for which no sentence is quoted: tumor (4 papers); cancer (1); Liddle syndrome (1); lung carcinoma (1); renal cell carcinoma (1).